POSTN (periostin)
Diseases named in the same sentence as POSTN in open-access papers (continued):
Sharing a sentence is not in itself a finding about the gene and the disease.
Telangiectasia (1 paper, 2022). Telangiectasias refer to small dilated blood vessels located near the surface of the skin or mucous membranes, measuring between 0.5 and 1 millimeter in diameter. "Nevertheless, in our current study, circulating periostin did not correlate with PH or other SSc related vascular complications, including digital ulcers or telangiectasias." (PMID 36369212, 2022).
testicular cancer (1 paper, 2025). A primary or metastatic malignant neoplasm that affects the testis. "However, with regard to testicular cancer, there are no reports of POSTN expression in human and canine testicles, and there are only two studies on PDPN in humans." (PMID 41361308, 2025).
testicular tumours (1 paper, 2025). "The upregulation of the POSTN and PDPN genes observed in canine testicular tumours raises important questions about the fundamental regulatory mechanisms involved." (PMID 41361308, 2025). "Analysing POSTN and PDPN expression in neoplastic cells of testicular tumours, we observed that their expression was significantly lower in LCTs than in SCTs and SEMs, both in percentage of positive cells and intensity." (PMID 41361308, 2025). "The expression of the POSTN and PDPN genes at the mRNA level was found in 100% (n = 28) of the analysed testicular tumours." (PMID 41361308, 2025). "The expression of POSTN and PDPN has been demonstrated for the first time in canine spontaneous testicular tumours, indicating their participation in the process of testicular carcinogenesis in dogs, as was already suggested for PDPN in human testicular tumours." (PMID 41361308, 2025). "The higher expression of POSTN and PDPN observed in SCTs and SEMs, compared to LCTs, may reflect the different characteristics of testicular tumours in the dog and could have prognostic and therapeutic implications that encourage further investigation involving a larger number of samples." (PMID 41361308, 2025).
tongue cancer (1 paper, 2024). A malignant neoplasm affecting the tongue. "Our future work will be to evaluate the association of POSTN exon 21 with the invasion and metastatic potential of tongue cancer and to test the efficacy of a POSTN exon 21-specific neutralizing antibody as an inhibitor of lymph node metastasis." (PMID 39195230, 2024). "The results suggest the potential of a novel form of therapy for targeting POSTN exon 21 in tongue cancer that has acquired resistance to chemotherapy with CDDP." (PMID 39195230, 2024). "With this in mind, we focused on POSTN splicing variants, specifically PN1-2, in our pursuit of a novel treatment for tongue cancer." (PMID 39195230, 2024). "We have reported the importance of the inhibition of the periostin (POSTN) pathological splicing variant, including exon 21 (PN1-2), in various malignancies, but its influence is unclear in tongue cancer." (PMID 39195230, 2024). "The mechanism causing POSTN to splice with exon 21 in tongue cancer is unknown; that said, the targeting of pathological POSTN splicing variants with PN21-Ab might offer a safe and effective strategy for the treatment of tongue cancer." (PMID 39195230, 2024). "The strong expression of PN1-2 mRNA in histopathologically high-grade types suggests that POSTN exon 21 may be a marker that correlates with the grade of tongue cancer." (PMID 39195230, 2024). "In summary, we hypothesized that pathological POSTN with exon 21 expressed in stromal fibroblasts may confer chemotherapy resistance to tongue cancer cells via Akt activation and activate cell survival signals." (PMID 39195230, 2024). "POSTN exon 21 is a potential a biomarker of tongue cancer, and PN21-Ab could be the basis of a novel therapy for chemotherapy-resistant tongue cancer." (PMID 39195230, 2024).
tuberculosis (1 paper, 2013). A chronic, recurrent infection caused by the bacterium Mycobacterium tuberculosis. "Periostin was demonstrated higher expression at the protein level in the pseudotumors and tuberculosis patients than in the adjacent (P=0.016) and surrounding tissues (P=0.001)." (PMID 24273600, 2013).
ureteral tumors (1 paper, 2022). "Eight tumors, comprising five renal pelvic and three ureteral tumors, exhibited focal (less than 25%) weak epithelial periostin expression, and none of the examined tumors were judged to have high epithelial periostin expression." (PMID 35850759, 2022).
uterine fibroids (1 paper, 2022). "In compliance with that, we showed that CD44/Stro1++ stem cells-derived UF organoids express an elevated level of POSTN compared to the MMSC-derived organoids suggesting that UFSC are predisposed to form uterine fibroids." (PMID 35585291, 2022). "Previous studies defined the proteome of uterine fibroids and established that increased POSTN production is a hallmark of uterine fibroids regardless of MED12 mutation status." (PMID 35585291, 2022).
Varicose veins (1 paper, 2023). Enlarged and tortuous veins. "The colocalization analysis indicated that COLEC11, IRF3, LUM, POSTN, RSPO3, and SARS2 shared the same causal variant with varicose veins." (PMID 37404740, 2023). "As a result, eight proteins were found to be causally associated with varicose veins, including COLEC11, IRF3, LUM, POSTN, RPN1, RSPO3, SARS2, and VAT1." (PMID 37404740, 2023). "We identified eight plasma proteins that are significantly associated with the risk of varicose veins after Bonferroni correction (P < 2.495 × 10−5), with five being protective (LUM, POSTN, RPN1, RSPO3, and VAT1) and three harmful (COLEC11, IRF3, and SARS2)." (PMID 37404740, 2023). "The COLEC11, IRF3, LUM, POSTN, RSPO3, and SARS2 were considered to share the same variant of varicose veins." (PMID 37404740, 2023). "Five of eight proteins in primary analysis were finally identified as potential drug targets for varicose veins, including IRF3, LUM, POSTN, RSPO3, and SARS2." (PMID 37404740, 2023). "A comprehensive analysis indicated that IRF3, LUM, POSTN, RSPO3, and SARS2 might be potential drug targets for varicose veins." (PMID 37404740, 2023).
viral infection (1 paper, 2022). "Further studies with larger series, which investigate whether the lower periostin levels during exacerbations could predict a viral infection as the underlying etiology and studies on the variations of periostin levels during exacerbations secondary to viral infections are needed." (PMID 36326393, 2022). "Compared to stable period, exacerbation period serum periostin levels found significantly lower [5853 (2309–8427) pg/mL vs. 4479 (2766–6495) pg/mL; p = 0.05] and periostin levels were much lower in viral infection-induced exacerbations [2913 (893–4770) pg/mL vs. 7094 (4782–9596) pg/mL; p = 0.022]." (PMID 36326393, 2022).
tumor (574 papers, 2006 to 2026). "High expression of POSTN is associated with tumor nodules, microvascular invasion, edmodson grade, and tumor-lymph node-metastasis (TNM) stage, affecting the prognosis of patients and decreasing overall survival." (PMID 41018265, 2025). "In contrast, periostin levels increase in response to tissue injury, irrespective of etiology, and are elevated in conditions associated with fibrosis, inflammation, or neoplasia." (PMID 41156134, 2025). "The expression level of POSTN is often upregulated and is associated with tumor aggressiveness and poor prognosis in HCC patients." (PMID 41018265, 2025). "In humans, POSTN expression has been detected not only in cancer-associated fibroblasts (CAFs), but also in the cells of multiple tumour types, including breast, ovarian, lung, colon and pancreatic cancers." (PMID 41361308, 2025). "POSTN is significantly elevated in tumor tissues compared to normal tissues, and high expression levels of POSTN are associated with poorer overall survival." (PMID 41018265, 2025). "An interesting finding in the mapping of scaffold proteins associated with tumor proliferation was the tumor-suppressive nature of the periostin protein, associated with reduced tumor proliferation." (PMID 41149224, 2025). "To elucidate the underlying mechanism how the tumor cells derived POSTN promote fibrosis in HSCs, we identified potential binding partners through string analysis." (PMID 39762921, 2025). "This recruitment, together with the presence of POSTN+ cancer-associated fibroblasts (CAFs) and endothelial cells, forms a distinctive “triad structure” that facilitates tumor growth and ICC progression." (PMID 41425545, 2025). "Studies have shown that overexpression of POSTN is associated with tumor aggressiveness, late metastasis and poor prognosis." (PMID 41018265, 2025). "Taken together, POSTN promotes the gathering of MDSCs in tumor metastases, moreover, its deficiency represses the immunosuppressive function of MDSCs." (PMID 39947253, 2025). "In solid tumors, high POSTN expression is associated with a more aggressive tumor behavior, advanced stage, and poor prognosis." (PMID 40076457, 2025). "By secreting periostin, GSCs recruit Tumor-Associated Macrophages (TAMs) into the tumor mass, where periostin-integrin αvβ3 binding initiates their pro-tumoral activation." (PMID 40386781, 2025). "Periostin (POSTN) is a secreted extracellular matrix protein that plays a role in attracting M2-type tumor-associated macrophages (TAMs), which are monocyte-derived macrophages from peripheral blood, to facilitate the growth of GBM." (PMID 40143207, 2025). "This interaction, along with the presence of POSTN+ cancer‐associated fibroblasts (CAFs) and endothelial cells, forms a unique “triad structure” that fosters tumor growth and ICC progression." (PMID 39716897, 2024). "As part of our study, we analyzed POSTN expression in tumor cells and tumor stroma and assessed its association with the pro-angiogenic factors (CD31, CD34, CD105, VEGF-A) in NSCLC." (PMID 39272978, 2024). "POSTN levels were significantly associated with tumor volume (P < 0.0001) and TNM stages (P < 0.0001) of BCa." (PMID 38504252, 2024). "Several studies have found that the overexpression of POSTN in tumor stroma is associated with more aggressive tumors, advanced stage or poor prognosis, and shorter overall survival in various cancers." (PMID 39195230, 2024). "There are also reports of decreased TNBCs secreting POSTN, accompanied by decreased numbers of M2 tumor-associated macrophages and tumor blood vessels." (PMID 39272982, 2024). "The POSTN mRNA level was also higher in CAL-27 cell lines of BM-MSC-HNSCC tumours, which was associated with a high pathological grade, proliferation rate, tumour volume and lymph node metastasis." (PMID 39120301, 2024).
tumor (continued). "Immunohistochemistry using tissue microarrays (TMAs) was used to assess the expression of POSTN (in tumor cells and cancer-associated fibroblasts [CAFs]) and the pro-angiogenic factors." (PMID 39272978, 2024). "Among 3372 captured cells, a large group of RMC cells was identified along with TAMs and other CD45-expressing immune cells (Natural killers, neutrophils and T-cells), POSTN-expressing CAFs, and an unexpected population of tumour-associated TAL2/3 cells." (PMID 37236926, 2023). "Next, to examine how the loss of Periostin affects the promotion of tumor growth following cardiac remodeling, LLC cells were subcutaneously implanted into the flanks of male POSTN(−/−) mice." (PMID 38139195, 2023). "Collectively, the data suggests that loss in Periostin leads to alteration in the levels of multiple secreted proteins that compensate and mediate the tumor-promotion phenotype following TAC in POSTN(−/−) mice." (PMID 38139195, 2023). "Significant associations between stromal POSTN expression and tumor metastasis to the peritoneum and distant organs were also identified." (PMID 36765564, 2023). "In short, they found that higher stromal periostin levels were correlated with worse clinical features and poorer prognosis, while periostin expression in tumor cells seemed to be associated with better patient outcomes." (PMID 38049490, 2023). "In the validation phase, SPOCK1 and POSTN have highly expressed in tumor cells and CAF for CRC, and the expressions associated with CAF have a poor prognosis and late clinical stage of CRC." (PMID 36611136, 2023). "Mechanistically, periostin recruits M2 tumor-associated macrophages to increase growth, as well as migration, proliferation, and angiogenesis." (PMID 37370851, 2023). "The results from CIBERSORT and TIMER revealed that SPOCK1 and POSTN were associated with tumor-infiltrating immune cells, especially macrophages and neutrophils." (PMID 36611136, 2023). "The tumor-promotion phenotype was preserved in TAC-operated POSTN(−/−) mice despite the loss of Periostin expression." (PMID 38139195, 2023). "They reported that periostin is expressed in both cancer cells and stromal cells, and its expression in tumor cells and stroma associates with clinical features including age, histological type, tumor recurrence, and prognosis." (PMID 38049490, 2023). "POSTN is highly expressed, mainly by stromal cells such as CAFs and to a lesser extent by tumour cells, and this is frequently associated with poor prognosis and metastasis in solid tumours." (PMID 35260891, 2022). "In ovarian and colorectal cancer, others have shown that overexpression of POSTN in tumor and stromal cells has been associated with poor survival, chemoresistance, tumor proliferation, and inhibition of immune cell activity." (PMID 35884543, 2022). "We identified that collagen-receptor, DDR2, is an upstream regulator of periostin in cancer-associated fibroblasts and that this interaction promotes tumor metastasis." (PMID 35884543, 2022). "This review comprehensively integrates the multiple roles of periostin and its variants in non-neoplastic diseases, proposes the utility of periostin as a biological biomarker, and provides potential drug-developing strategies for targeting periostin." (PMID 36611844, 2022). "High POSTN expression levels are usually associated with aggressive tumor behavior and poor prognosis in cancer." (PMID 36172351, 2022). "Several studies have found that periostin overexpression in tumor stroma and cancer epithelial cells is associated with a more aggressive tumor, advanced stage or poor prognosis, and shorter overall survival in various cancers." (PMID 36224629, 2022). "Periostin-deficient MDSCs displayed reduced activation of ERK, AKT and STAT3 and periostin deficiency decreased the immunosuppressive functions of MDSCs during tumor progression." (PMID 35719975, 2022).
tumor (continued). "High levels of POSTN are found to be associated with aggressive tumor behaviour, tumor progression, resistance to treatment and hence, bad prognosis." (PMID 33420101, 2021). "Granulin secretion by MAMs activated resident hepatic stellate cells into myofibroblasts that produced periostin, causing a fibrotic milieu that supports metastatic tumor growth." (PMID 34336660, 2021). "When studied in OSCC/HNSCC, the expression of POSTN in the epithelium is associated with a more aggressive tumour phenotype in OSCC, as was determined by the mRNA and IHC expression." (PMID 33739025, 2021). "In PDAC tissues, POSTN expression is strongly upregulated in cancer epithelial cells, PSCs, and stroma, and is associated with poor prognosis and worse tumor differentiation grade." (PMID 34944807, 2021). "Periostin, an extracellular matrix, is one of the overexpressed proteins in many human cancer cells which are associated with tumor growth, metastasis and angiogenesis." (PMID 32751068, 2020). "Higher expression (score 2 or 3) of periostin in the tumor stroma, as well as in cancer cells, was associated with higher degree of desmoplastic reaction (χ2 test p < 0.001 and p = 0.037, respectively)." (PMID 31936272, 2020). "For example, changes typical of tumor stroma, such as the appearance of the fibronectin splice variants ED-A or ED-B, laminin-332, periostin and tenascin-W, can be histochemically analyzed in tissue biopsies (and references therein)." (PMID 33379400, 2020). "Previously, we have identified that the expression of periostin in the stroma of prostate cancer is associated with aggressive clinical behavior of the tumor." (PMID 32719746, 2020). "Similar to the case of fibronectin, the expression of periostin in tumor stroma was found to be associated with the source of tumor samples." (PMID 31936272, 2020). "Further multivariate analysis revealed that tumor thrombus and POSTN expression are independent risk factors for survival." (PMID 33083453, 2020). "The progression of CRC is determined by the driving force of periostin (PN) from cancer‐associated fibroblasts (CAFs) in the tumour microenvironment." (PMID 32990415, 2020). "The results strongly suggest that pharmacological inhibition of cancer-specific variants of periostin can effectively suppress mesenchymal tumor cell expansion and overcome chemoresistance." (PMID 29507310, 2018). "In other study, POSTN expression was associated with tumor nodules, microvascular invasion, Edmodson grade, TNM stage, and higher levels of vascular endothelial growth factor (VEGF) expression." (PMID 29946533, 2018). "In MCF10DCIS tumors, human nuclei+/CD44high cancer cells detected by a human-specific CD44 antibody at the tumor-stroma interface were mostly E-cadherin- and associated with periostin at laminin-5+ basement membrane, which became prominent after PTX treatment." (PMID 29507310, 2018). "Studies carried out in patients have revealed that high expression of POSTN in tumor stroma was significantly associated with shorter overall survival rates." (PMID 29946533, 2018). "M2 tumor-associated macrophages are recruited through association of their αvβ3 integrins with Periostin to favor tumor growth." (PMID 29156849, 2017). "In particular, the role of the periostin pathway in the recruitment of tumor-associated macrophages, and the proposed contribution of exosome-derived integrins in the metastatic spread will be discussed." (PMID 28933725, 2017). "Periostin expression by cancer cells and/or cancer-associated stroma has been found to correlate with tumor progression and clinical outcome in various types of cancer." (PMID 29161296, 2017). "In the present study, TGF-βs, especially TGF-β3, was found to be associated with the POSTN expression in CAFs during the co-culture with tumor cells." (PMID 26857387, 2016). "High stroma POSTN expression was associated with higher prevalence of high POSTN expression tumor cells (correlation coefficient = 0.219; p < 0.001)." (PMID 26716408, 2016).